CCND1 (cyclin D1)
Diseases named in the same sentence as CCND1 in open-access papers (continued):
Sharing a sentence is not in itself a finding about the gene and the disease.
breast cancer (continued). "Because estrogen is mitogenic, and thus leads to increases in both cyclin D1 and CDK4/6 activity, it causes excess proliferation in hormone-regulated breast cancers." (PMID 34830174, 2021). "The cyclin D1 gene is overexpressed in human breast cancer and is required for oncogene-induced tumorigenesis therefore the mechanism by which cyclin D1 governs tumor metabolism is of broad interest." (PMID 34631530, 2021). "The classification of breast cancer based on the coding region identified potential genetic targets including the CCND1 gene, which is amplified in 30 to 58% of breast cancers; the estrogen receptor (ERα); and/or progesterone receptor (PR) and Her2." (PMID 33485378, 2021). "We found low expression of CCND1 (0.1761) was found to be correlated with better OS for patients with breast cancer (n=1402)." (PMID 33438725, 2021). "Cyclin D1 overexpression characterizes numerous human cancers; nearly 90% of mantle cell lymphomas and 50% of breast cancers exhibit cyclin D1 overexpression." (PMID 33444446, 2021). "As a result, STAT3 upregulated the expression of breast cancer-aggravating genes, such as CCND1 and MMP2, thereby enhancing the proliferation and migration of breast cancer cells." (PMID 34335938, 2021). "It functions as a potential oncogene that interacts with HDGF to recruit c-Jun and thus stimulates CCND1 expression to induce cell cycle transition, finally promoting cell proliferation in breast cancer." (PMID 34774047, 2021). "The amplification of Her2, S100A and CCND1 have biological significance in breast cancer pathology, and amplification of c-MYC is related to high-grade malignancy." (PMID 34868925, 2021). "The inhibitory effect of ELF5 in breast cancer was abolished when Cyclin D1 was overexpressed or CCND1 was knockdown." (PMID 33742100, 2021). "A study using a mouse mammary tumor virus model of breast cancer identified CCND1 gene amplification with positive IHC staining in 40% of breast cancer samples." (PMID 33920506, 2021). "Correlation of high cyclin D1-related elevation with Rb phosphorylation was also observed in >100 high-grade breast carcinomas." (PMID 33920506, 2021). "It is an important regulator of the cell cycle that performs a central role in the pathogenesis of cancer and determines uncontrolled cellular proliferation; the cyclin D1 gene (CCND1) is amplified in approximately 20% of mammary carcinomas." (PMID 34903946, 2021). "In spite of the strong evidence demonstrating the role of overexpression of Ki-67 and Cyclin D1 markers in breast carcinomas, clinical and pathological data remain to be discussed." (PMID 34394279, 2021). "The abnormal expression of cyclin D1 has been well-documented in human BC and overexpressed in more than 50% of breast cancers." (PMID 34201250, 2021). "Further data establish that Cyclin D1 is important for the development of mammary cancers induced by different oncoproteins such as receptor tyrosine-protein kinase erbB-2 (Her2/neu) and v-Ha-ras, but not those induced by c-Myc or Wnt-1." (PMID 33317149, 2020). "Here, we identify a lncRNA, DILA1, which interacts with Cyclin D1 and is overexpressed in tamoxifen-resistant breast cancer cells." (PMID 33139730, 2020). "For the treatment of breast cancer, some researchers have studied the estrogen receptor alpha-mitogen-activated protein kinases/Akt-cyclin D1/B-cell lymphoma-2 signaling pathway, regulation of myeloid cell leukemia-1, cyclin D1, and C-myc genes, and more." (PMID 33542691, 2020). "In breast cancer, it was shown that cyclin D1 expression, the major regulator of the G1-S progression of the cell cycle, was controlled by PIK-3/AKT signaling." (PMID 32499871, 2020). "The results confirmed that CCND1 was highly expressed in breast cancer tissues and PER1 was low expressed in breast cancer tissues, which is consistent with the results of our data analysis." (PMID 33365308, 2020).
breast cancer (continued). "Next, the effects of LY294002, a PI3K/AKT inhibitor, were further examined on GSK3β (Ser9) phosphorylation and Cyclin D1 expression in the 2 breast cancer cell lines." (PMID 32944401, 2020). "In ERα-positive cells, the adiponectin produces the specific recruitment of a coactivator complex inducing Cyclin D1 transcription, sustaining ERα-positive breast cancer cell proliferation." (PMID 33317149, 2020). "Second, a high dose of rapamycin is required to induce G1 arrest by attenuating phosphorylation of 4E-BP1 and expression of cyclin D1 in breast cancer cell lines." (PMID 32213867, 2020). "The constitutively active, GTP-bound variant of RAC1, RAC1b, is preferentially expressed in both colon and breast cancers, enhancing the downstream activation of NF-κB and the induction of cyclin D1 expression in a variety of solid tumors." (PMID 32545340, 2020). "It was found that there is an over-expressed T1 gene in human breast cancer cells, and T3 inhibits the proliferation of mammary epithelial cells by inhibiting the expression of cyclin D1 and T1, thereby inhibiting the proliferation of breast cancer cells." (PMID 32762667, 2020). "In breast cancer cells, the overexpression of this miR-503 was shown to reduce cell proliferation through the induction of a G1 cell cycle arrest by targeting CCND1." (PMID 32365562, 2020). "In this study, we investigated lncRNAs that interact with Cyclin D1 and examined their functional significance in tamoxifen resistance of breast cancer." (PMID 33139730, 2020). "In the present study, we demonstrate that SHP2 modulates the proliferation of breast cancer cells in vitro and tumor growth in vivo by regulating Cyclin D1 expression and thereby accelerating cell cycle progression." (PMID 32944401, 2020). "SHP2 knockout substantially increased p-Cyclin D1 (T286) expression in breast cancer cells when the action of the proteasome was blocked." (PMID 32944401, 2020). "In this respect, we previously observed that SrcDN expression and selective c-Src tyrosine-kinase inhibitors diminish cyclin D1 expression and cell cycle progression at G1-phase in breast cancer cells." (PMID 32673341, 2020). "Our study demonstrates that S100P enhances cell proliferation by activating CCND1, and promotes cell migration and invasion through downregulating E-cadherin and upregulating Vimentin in breast cancer in vitro." (PMID 33042844, 2020). "In vitro, 20(S)-Rg3 significantly inhibits the proliferation of MDA-MB-231 and MCF-7 breast cancer cells by decreasing the expression of cyclin D1 and cyclin A as well as arresting the cells in the G-1 phase." (PMID 32823812, 2020). "Cyclin D1 overexpression is reported in >50% of human breast cancers and dysregulation of cyclin D1 expression or function contributes to altered cell cycle control during breast cancer development." (PMID 33027908, 2020). "Further elegant studies demonstrate that Cyclin D1 governs a specific cluster of miRNA, which correlates with ERα positivity in breast cancer and with Wnt signaling activation." (PMID 33317149, 2020). "An increase of nuclear Cyclin D1 levels in stromal fibroblast of 914 breast cancer patients has been demonstrated, predicting poor outcome." (PMID 33317149, 2020). "Knocking down DILA1 decreased the expression of Cyclin D1 protein and reversed tamoxifen resistance of breast cancer cells both in vitro and in vivo." (PMID 33139730, 2020). "Collectively, these results demonstrated that the knockout of SHP2 delayed the G1-to-S phase transition and decreased Cyclin D1 expression in breast cancer cells." (PMID 32944401, 2020). "In the present study, the blockage of proteasome activity by MG132 increased the level of phosphorylated Cyclin D1 in breast cancer cells." (PMID 32944401, 2020). "Gain of the CCND1 and CDK4 and loss of the CDKN2A (p16) and CDKN2C (p18) genes are present in patients with luminal B breast cancer and poor prognosis of and negatively regulated by the cell cycle pathway." (PMID 33110086, 2020).
breast cancer (continued). "Overall, this study provides first comprehensive evidence on the involvement of canonical signaling of TLR3 using MyD88–cyclin D1-mediated breast cancer cell proliferation." (PMID 33072559, 2020). "The genetic deletion of EZH2 resulted in down-regulation of cyclin D1 in breast cancer and in up-regulation of p21 in ovarian cancer, thereby causing cell-cycle arrest at the G1/S phase." (PMID 33330073, 2020). "In summary, this study demonstrates the novel role of lncRNA DILA1 in regulating Cyclin D1 protein at the posttranslational level and leading to tamoxifen resistance of breast cancer." (PMID 33139730, 2020). "It raises the possibility that lovastatin activation of p38MAPK signalling not only modulates survivin and p21 as reported here, but also reduces cyclin D1 in breast cancer cells." (PMID 31821701, 2020). "In sensitive breast cancer cell lines ATRA can down-regulate the expression of some anti-apoptotic molecules as Bcl-2, cdk2, cyclin D1, and survivin, that are overexpressed in one third of breast cancer types." (PMID 32012980, 2020). "This study shows the previously unappreciated importance of post-translational dysregulation of Cyclin D1 contributing to tamoxifen resistance in breast cancer." (PMID 33139730, 2020). "We have previously shown how TF/FVIIa signaling induce transcription of the cyclin-D1 gene in breast cancer cells by using real-time PCR." (PMID 32458278, 2020). "Previous studies have shown that cyclin D1 and cyclin E are essential for the emergence of tamoxifen resistance in breast cancer cells." (PMID 33362547, 2020). "Here, the authors demonstrate that PLK1 inhibition is a potential therapeutic target in CCND1-driven and in RB-positive Palbociclib-resistant breast cancers." (PMID 32792481, 2020). "In the present study, we demonstrated that SHP2 functions as a key modulator of the proliferation of breast cancer cells by promoting the G1-to-S phase transition through regulating Cyclin D1 stability via the PI3K/AKT/GSK3β signaling pathway." (PMID 32944401, 2020). "For example, in breast cancer, the CCND1 amplification group showed a lower median ESTIMATE score (−669.12 vs. −245.99, P = 0.0130)." (PMID 32903763, 2020). "Cyclin D1 protein is very frequently (50–70%) overexpressed in breast cancer and its gene CCND1 is also frequently (9–30%) amplified in these tumors." (PMID 32210163, 2020). "Most of these partners of Cyclin D1 found in B-cell lymphoma and myeloma cells, are also present in solid tumors such as breast cancer, squamous cell carcinoma, and colorectal cancer." (PMID 33317149, 2020). "Another study in breast cancer found that Sox2 and β-catenin synergistically promoted the transcription of CCND1, resulting in enhanced proliferation and tumorigenesis." (PMID 33302540, 2020). "In the present study, we found that treatment of triple-negative MDA-MB-231 breast cancer cells with ISL inhibited cancer cell growth through blocking the cell cycle by reduction of cyclin D1 expression." (PMID 32164337, 2020). "More intriguingly, we found the expression levels of E2F1 and CCND1 were positively correlated with the methylation of miR-93 promoter locus, using breast cancer samples (n = 614) in TCGA database." (PMID 32796817, 2020). "TSA inhibit tumor growth of breast cancer cells by degradation of Cyclin D1 and inhibition of ER-α transcription in ER-α positive breast cancer cells." (PMID 32257110, 2020). "In order to characterize the function of membrane-associated cyclin D1, studies were conducted in the human diploid fibroblast cell line (MRC-5) and human breast cancer samples." (PMID 32948740, 2020). "Cyclin D1 expression has long been known to be elevated and predictive of poor clinical outcome in ER+ breast cancer." (PMID 32226926, 2020).
breast cancer (continued). "Since Cyclin D1 and Dicer expressions significantly correlate in luminal A and basal-like subtypes of human breast cancer, authors conclude that Cyclin D1 through Dicer coordinates microRNA biogenesis in these breast cancer subtypes." (PMID 33317149, 2020). "Cyclin D1 (CCND1)-upstream intergenic DNA repair 1 and 2 (lncRNA CUPID1/2) mediates the breast cancer risk at 11q13 by modulating the cellular response to DNA damage." (PMID 32429086, 2020). "In breast cancer cell lines, Sox2 increases mammosphere formation, up-regulates CCND1, the cyclin D1-encoding gene, thus facilitating the G1/S transition of the cell cycle, activates the WNT signaling pathway and the epithelial-to-mesenchymal transition." (PMID 33553286, 2020). "In liver and breast cancer cells, knockdown of CCND1 gene leads to increased PPARα transcriptional activity, expression of PPARα target genes, and fatty acid oxidation." (PMID 33317149, 2020). "Lactadherin, on the other hand, regulates Cyclin D1 and D3 expression, leading to an increase in tumorigenic potential of epithelial breast cancer cells." (PMID 31941923, 2020). "Here, the authors demonstrate that the LncRNA DILA1 contributes to tamoxifen resistance in breast cancer by binding to Cyclin D1 and preventing its degradation." (PMID 33139730, 2020). "In ER+/PR+ cells, P4 promotes proliferation via a cyclin D1-dependent, cell-intrinsic mechanism and overexpression and amplification of Cyclin D1 correlates with poor prognosis in women diagnosed with ER+/PR+ breast cancers." (PMID 32867363, 2020). "Recent studies have also suggested that CCND1 is involved in the process of cancer initiation and progression in multiple cancers, including breast cancer, lung cancer, and bladder cancer." (PMID 33363164, 2020). "Overexpression of cyclin D1 in breast cancer cells is also another mechanism of endocrine resistance." (PMID 34968306, 2020). "We also confirmed the expression of NOTCH4, SLUG, GAS1 and CCND1 in different subtypes of breast cancer cell lines and observed expected expression patterns." (PMID 32104513, 2020). "A study showed that CCND1 in MCF-7 breast cancer cells using CKI was significantly down-regulated compared with untreated cells.Therefore, CCND1 is predicted to be a significant target of CKI for the treatment of GC." (PMID 32020871, 2020). "Interrogation of TCGA breast cancer cohort confirmed that the 11q13 amplification (as captured by amplification of CCND1 gene) is observed in 34.7% of cases with the 8p11.23 amplicon (as represented by amplification of ZNF703 gene)." (PMID 32987805, 2020). "This possibility is also supported by frequent lesions in the RB/E2F pathway in breast cancer, including loss of RB1, CDKN1B (encoding p27), and CDKN2A as well as amplification of CCND1." (PMID 32985974, 2020). "SHP2 is required for the proliferation of breast cancer cells in vitro and tumor growth in vivo through regulation of Cyclin D1 abundance, thereby accelerating cell cycle progression." (PMID 32944401, 2020). "More recent studies show that the expression of the Cyclin D1 increases in human cancer stroma, promoting tumor inflammation, angiogenesis, and stem cell expansion in advanced breast cancer." (PMID 33317149, 2020). "The decrease in Cyclin D1 caused by SHP2 knockout was restored after MG132 treatment, thus indicating that SHP2 knockout triggered the degradation of Cyclin D1 in breast cancer cells via the proteasome-mediated proteolysis pathway." (PMID 32944401, 2020). "Cyclin D1 plays an important role in the development and progression of several cancers including breast cancer and bladder cancer." (PMID 32792963, 2020). "Pin1-deficient mice inhibit the massive proliferation of breast epithelium in pregnancy through reducing cyclin D1 levels and decreases β-catenin expression in breast cancer." (PMID 32258027, 2020).
breast cancer (continued). "Several studies reported that v-src causes ATF2 and CREB to bind the CRE/ATF site of the cyclin D1 gene, leading to transcription of cyclin D1 in MCF7 human breast cancer cells." (PMID 33198803, 2020). "Studies have shown that matrine can mediate the expression of CCND1 in breast cancer cells and thus inhibit cancer cells." (PMID 32728182, 2020). "Elevated CCND1 is known to suggest poor prognosis in many cancers, such as colorectal cancer, breast cancer, and multiple myeloma." (PMID 32733557, 2020). "Overexpression of PIN1 increases the PTOV1 expression as a novel interactome of PIN1, and knockdown of both genes inhibits the expression of β-catenin, cyclin D1, and c-Myc in breast cancer MDA-MB-231 cells." (PMID 32258027, 2020). "We anticipate that DACH1 mutations result in loss of transcriptional repression of these regulators resulting in uncontrolled cell cycle progression in endometrial cancer, similar to DACH1’s control of the cell cycle via cyclin D1 in breast cancer." (PMID 33378353, 2020). "Cyclin D1 deficiency has been shown to impair mammary epithelial proliferation while cyclin D1 and CDK4 are necessary for breast cancer development in mice and cyclin D1 is overexpressed in the majority of human breast cancers." (PMID 32012988, 2020). "The latest research in the last 2 years found that LEM4 (LEM structural protein), which is highly expressed in breast cancer-resistant cells, promotes the transcription of cyclin D1 through ligand-independent activation of receptors." (PMID 33362547, 2020). "CCND1 is the important driver gene of the 11q13 amplicon, and PPFIA1 amplification was found in all CCND1-amplified breast cancers." (PMID 32410585, 2020). "In breast cancer patients who are BRCA1 mutation carriers, CCND1 expression was significantly reduced." (PMID 32685473, 2020). "The results show the significance of targeting VEGFR-2 and cyclin D1 in Saudi luminal-A breast cancer patients, and the effect of combining HAA2020 and dinaciclib on those targets in the MCF7 model." (PMID 33050377, 2020). "Our findings uncovered for the first time that E2F1 and CCND1 positively modulated PTX-resistance in breast cancer cells." (PMID 32796817, 2020). "In conclusion, S100P enhances the proliferation, adhesion, migration, and invasion of breast cancer cells through the regulation of NF-κB, CCND1, E-cadherin and Vimentin." (PMID 33042844, 2020). "CCND1 is a well-studied breast cancer driver gene, the amplification of which is more prevalent in luminal subtypes compared to Her2 and basal-like." (PMID 32605588, 2020). "Mechanistically, DILA1 inhibits the phosphorylation of Cyclin D1 at Thr286 by directly interacting with Thr286 and blocking its subsequent degradation, leading to overexpressed Cyclin D1 protein in breast cancer." (PMID 33139730, 2020). "CCND1 polymorphisms rs614367 and rs498136 are intergenic SNPs which affects the regulation and expression of CCND1 gene in breast cancer and malignant melanoma, respectively." (PMID 32373934, 2020). "Cyclin D1 plays an important role in breast cancer development and progression through cyclin-dependent kinase (CDK)-dependent and CDK-independent interactions." (PMID 32405344, 2020). "The subsequent upregulated Cyclin D1 protein accelerated cell proliferation and resulted in tamoxifen resistance in breast cancer cells." (PMID 33139730, 2020). "In the present review, we will summarize the current scientific evidences that highlight the involvement of Cyclin D1 in the pathogenesis of different types of cancer, best of all in breast cancer." (PMID 33317149, 2020).